ENSG00000252404
Synonyms: LOC124900441
Gene: Small Cajal body-specific RNA gene on chromosome 1 (9,082,696 to 9,082,879, forward strand). Ensembl gene ENSG00000252404.
Gene Ontology:
Biological process: RNA processing
Cellular component: nucleolus